CTSB (cathepsin B)
Diseases named in the same sentence as CTSB in open-access papers (continued):
Sharing a sentence is not in itself a finding about the gene and the disease.
cancer (continued). "Moreover, we compared CTSB/L expressions between various cancers and matched normal tissues, and investigated their genetic alteration and prognostic values in pan-cancer." (PMID 35155389, 2022). "Nonetheless, inhibiting the overexpression of CTSB and maintaining its dynamic balance in organism may help control or alleviate CTSB-related cancer and inflammatory diseases." (PMID 35872750, 2022). "Furthermore, we used a valine citrulline (Val-Cit) linker which is cleavable by cathepsin B, a protease highly expressed in cancer cells." (PMID 35574389, 2022). "Cathepsin B plays a major and important role in development of cancer and its progression." (PMID 35260133, 2022). "The drug release studies of MTX–G–P4LDN–E2 demonstrated the gradual release of the drug in the presence of the enzyme cathepsin B. This enzyme belongs to a family of papain-like proteases, and it is usually found in the lysosome, whereas it is upregulated in cancers." (PMID 35160746, 2022). "A lysosomal protease termed cathepsin B was also found to be upregulated in different cancer types, including brain, lung, and colon tumors, thus providing an important advantage for target delivery inside the cancer cells." (PMID 36297630, 2022). "Nanoparticles may be digested into smaller particles by the enhanced pericellular cathepsin B released by malignant tumors, according to the findings of this study." (PMID 35903701, 2022). "Cathepsin B and cancer procoagulant factor were widely described to participate in TCIPA." (PMID 35814405, 2022). "Importantly, the PD-NPs selectively released free DOX in cathepsin B-overexpressed cancer cells after PD-L1-mediated endocytosis, which provoked strong antitumor immune responses through combining of PD-L1 blockade and ICD." (PMID 35265195, 2022). "In cancer cells, overexpressed cathepsin B clefted the nanoformulation and released DOX and SMAC." (PMID 34834387, 2021). "Dipeptide linkers, also known as enzyme cleavable linkers, ensure that the ADC remains stable in the circulation and only undergoes cleavage in the cancer cell intracellular lysosomal environment via lysosomal proteases, such as cathepsin B, which are overexpressed in several cancer cell types." (PMID 34063364, 2021). "Furthermore, inverse correlations of CTSB expression and prognosis of cancer patients have been frequently reported." (PMID 32385587, 2021). "CTSB, a kind of lysosomal cysteine protease, has been reported to be a potentially effective biomarker as well as an important contributor to the progression of different types of cancers." (PMID 33628106, 2021). "To determine whether excessive ROS is essential for LMP increase and subsequent cathepsin B release, we treated the cancer cells with acetylcysteine (NAC), a well-known ROS scavenger." (PMID 32848130, 2020). "Cathepsin B and uPAR have key roles in cancer cell migration and invasion." (PMID 32764572, 2020). "High cathepsin B expression is found in a variety of human cancers." (PMID 33335896, 2020). "CTSB is a target candidate in LUSC-PGS and GBM-PGS, encoding a member of the cathepsin protein family which remodel the extracellular matrix to facilitate cancer invasion and metastasis." (PMID 33277589, 2020). "The cancer secretome may originate from cancer cells themselves, and to evaluate if the observed high expression of CTSB originated in the cells themselves, we measured CTSB levels in Nthy-ori-3-1, SNU790, TPC-1, and 8505C cell lines using immunoblotting." (PMID 33333840, 2020). "Indeed, experimental down-regulation of Cathepsin B demonstrated reduced motility and invasion of cancer cells." (PMID 32050622, 2020). "Interestingly, several genes, such as DRAM1, SERPINE2, SDC2 and CTSB, have been shown to correlate with chemotherapy efficiency in cancers 20-24." (PMID 31660072, 2019). "The possible link between CTSB and cancer was first postulated many years ago35,36." (PMID 30796200, 2019).
cancer (continued). "CTSB, a multifunctional proteolytic enzyme, plays an important role in cancer progression." (PMID 31450586, 2019). "While CTSB has been implicated in oncogenic processes in several types of cancer, to our knowledge there are no published data demonstrating CTSB’s function in RCC12." (PMID 30796200, 2019). "Together, the obtained data show that the concept of cathepsin B‐cleavable prodrugs can be transferred to the class of targeted therapeutics, allowing the development of optimized tyrosine kinase inhibitors for the treatment of cancer." (PMID 30566287, 2019). "Once the activity of Cathepsin B was inhibited, the ROS generation was attenuated in cancer cells." (PMID 31296864, 2019). "Cathepsin B, a cysteine protease, also plays role at many stages of cancer growth." (PMID 32184869, 2019). "Interestingly, the cathepsin B expression pattern that we report here almost parallels that reported with GB cancer stem cells." (PMID 30949483, 2019). "CTSB was found to participate in autophagy and immune resistance, which could be a potentially biomarker for various cancers." (PMID 30093865, 2018). "The expression of cathepsin B is highly prognostic in various types of cancers, including GBM." (PMID 30046941, 2018). "Cathepsin B (ctsbb) promotes tumorigenesis and cancer progression in human cells." (PMID 29715317, 2018). "In addition, recent studies reported that v-ATPase inhibition impairs the activity of cathepsin B in cancer cells." (PMID 30204757, 2018). "In cancer cells v-ATPase inhibition by archazolid impaired the mannose-6-phosphate receptor-mediated trafficking from the trans-Golgi network to prelysosomal compartments resulting in a decrease of active lysosomal proteases like cathepsin B." (PMID 30204757, 2018). "Doxorubicin conjugated enzyme-cleavable precursors attached to silica coated magnetic nanoparticles by click chemistry, enables this NP moiety to release the drug efficiently when it comes in contact with cathepsin B which is usually overexpressed in cancer cells." (PMID 28492519, 2017). "Overall, CTSB appears to have various roles in cancer cells." (PMID 27031837, 2016). "In return, CTSB facilitates further CCK secretion by the cancer cells." (PMID 26700819, 2016). "The status of CTSB protein in carcinoma tissues is much higher than that in paracarcinoma tissues." (PMID 26896959, 2016). "Cathepsin B expression increases in many human cancers at mRNA, protein and activity levels." (PMID 26691339, 2015). "Moreover, owing to the increased expression of cathepsin B and changes in intracellular trafficking, several human cancers exhibit increased secretion of procathepsin B; additionally, cancer cells secrete active cathepsin B." (PMID 26674348, 2015). "In addition, Cathepsin B, a member of the lysosomal proteolytic enzyme Cathepsin family, has also been reported to play crucial roles in cancer invasion and metastasis." (PMID 24705283, 2014). "In addition, inhibition of Cathepsin B has been shown to attenuate cancer cell invasion and metastasis." (PMID 24705283, 2014). "Taken together, it suggested that hedgehog signaling might be activated in metastatic lung SCC, which could affect expression of CTSB that could promote cancer cell invasion." (PMID 24139065, 2013). "Among the potential molecular markers that could aid in diagnosis or prognosis of EmCa, some such as PKM2, LDHA and cathepsin B have already been explored for their therapeutic potential in other cancers." (PMID 21305022, 2011). "The ablation of key autophagy or lysosome-dependent cell death effectors, such as STAT3 and cathepsin B, could inhibit ferroptotic cancer cell death, whereas the knockout of SLC7A11 or GPX4 could reduce autophagy, thereby providing further protection against ferroptosis induced by Golgi stress." (PMID 41462678, 2025). "Therefore, targeting CTSB could have significant clinical relevance in the treatment of various cancers." (PMID 40411408, 2025).
cancer (continued). "However, aberrant expression of the cysteine protease CTSB is observed in the pathogenesis of many diseases, including neurological, immune, and cardiac diseases as well as cancer." (PMID 40411408, 2025). "In addition, recent studies suggest that Cathepsin B inhibitors exhibit therapeutic potential in treating cancers and brain injuries, indicating targeting Cathepsin B may help in several pathological conditions." (PMID 40294065, 2025). "Among them, Cathepsin B and Cathepsin D may be prognostic markers of cancer." (PMID 39080685, 2024). "Additionally, a peptide that is easily cleaved by the cysteine protease Cathepsin B was used as a linker for anchoring the PS Verteporfin onto the surface of gold nanoparticles so that upon cancer cell internalization of the nanoconjugate the PS is released after cleavage of the peptide linker." (PMID 37446050, 2023). "However, CTSB knockdown suppressed cancer cell proliferation." (PMID 37576397, 2023). "Intrigued by the observation that a cathepsin B-dependent cleavage activity on CD9-RFP recombinant protein is evident in a cathepsin B-overexpressing cancer cell line, we wondered whether the same phenotype could also be reproduced in a non-cancer cell line like HEK293 cells." (PMID 36579638, 2023). "In addition, the constructs were not only delivered to the extracellular vesicles fraction, but also correctly processed by cathepsin B protease as demonstrated by the differential ratio between the fusion products carrying the CS or NACS sequences in cancer cells." (PMID 36579638, 2023). "In addition, other stefins, CtsB and CtsC, actively regulate cancer cell proliferation." (PMID 35563761, 2022). "CTSB is not only produced in response to muscle activity, but for instance also by macrophages during perineural invasion, cartilage cells, by various types of cancer, where high CTSB expression often goes along with a less favorable prognosis, and by microglia in the central nervous system." (PMID 33655551, 2021). "Moreover, our initial goal to find drugs that could prevent invasion of HER2 inhibition resistant cancer models while retaining most of the activity of cathepsin B and thus the cell’s ability to undergo lysosome-dependent cell death was achieved." (PMID 33939112, 2021). "CTSB may provide a promising target for such novel cancer therapies." (PMID 30796200, 2019). "Opposed to effects on CTSB and as expected based on our previous observations, MTA1 negatively regulates E‐cad expression in primary tumor, a hallmark of EMT associated with metastasis, indicating the impact of MTA1 in the process of EMT and cancer cell ability to migrate to distant sites." (PMID 30027683, 2018). "The canonical proteolytic cascade that leads to enhanced cancer cell invasion is considered to be initiated by (pro)cathepsin B, which translocates from lysosomes to plasma membranes, where it may activate uPA, which in turn activates MMP-14, followed by activation of gelatinases MMP-2 and MMP-9." (PMID 28424417, 2017). "Many researchers concluded that CTSB might be a metastasis-related gene, and consequently in the clinic, it can serve as a predictor for therapeutic outcome or prognosis of patients with cancers." (PMID 26896959, 2016). "Importantly, this example serves as a prototype for development of biochemical tools for further analysis of proteases in cancer and clinically relevant, photoactivated inhibitors of CTSB with red-shifted absorbance to facilitate tissue penetration by low energy light for in vivo applications." (PMID 26562785, 2015). "Thus CTSB has long been considered as a candidate target in cancer therapy." (PMID 24588871, 2014). "Increased TRIP-Br1 promotes mitophagy through upregulating CTSB and CTSD, which in turn inhibits cancer cell apoptosis and ultimately promotes cancer cell survival." (PMID 39013891, 2024).
cancer (continued). "As a result, cathepsin B rapidly and specifically cleaved the FKFL linker to release BIM in the endosome of SKOV3 ovarian cancer cells and induced apoptosis to kill cancer cells." (PMID 38398021, 2024). "Notably, cathepsin D can activate the precursor of cathepsin B, which further activates cathepsin D and transports cathepsins B and D between cells through the actin skeleton and microtubules, thereby degrading the extracellular matrix and promoting cancer cell migration and invasion." (PMID 37833712, 2023). "In this study, the secretion of several proteases including cathepsin-B, MMP-1 and MMP-13 by cancer cells was shown to be significantly increased in response to the presence of galectin-3." (PMID 37055381, 2023). "For instance, a group of scientists described a method for bio-imaging cathepsin B (CTSB), one of the most promising biomarkers for a variety of malignant tumors that allowed for the effective early detection of tumors." (PMID 36986879, 2023). "The prodrug design was able to release FTY720 intact via cathepsin B. Importantly, the cytotoxicity of FTY720 can be masked when conjugated to mitigate the potential side effects of using FTY720 for cancer therapy." (PMID 36839802, 2023). "Within all the considered parameters, RT-qPCR showed a significantly higher expression of both genes (CTSB, p = 0.012; STFA, p = 0.007) in cancer tissues (T) than in surrounding healthy kidneys (NT)." (PMID 35563761, 2022). "In contrast, the silencing of CtsB and StfA significantly reduced the growth of RCC-derived cells, highlighting the importance of this balance in cancer cell biology." (PMID 35563761, 2022). "The current study aimed to determine CTSB and STFA mRNA expression between RCC cancer lesions and surrounding healthy renal tissue." (PMID 35563761, 2022). "Next, when cancer lesions occurred in both the kidneys, CTSB and STFA expression significantly increased compared to tumors occurring in the right (CTSB, p = 0.027) or the left kidney (STFA, p = 0.036), respectively." (PMID 35563761, 2022). "The overexpression of cathepsin B can be used for the imaging and photodynamic therapy (PDT) of cancer." (PMID 35631388, 2022). "Many different enzymes have been found to be highly expressed in cancer cells and tumor tissues, including matrix metalloproteinase 2 (MMP-2), Cathepsin B, and hyaluronidase (HAase)." (PMID 35631699, 2022). "Our results show that the immune cell infiltration was correlated with CTSB expression in most cancer types and CTSL expression in a part of the cancer types (COAD, STAD, LUAD, and LUSC) (respectively)." (PMID 35155389, 2022). "The results showed that CTSB/L had been positively related to most infiltrating immune cells and MHC molecules in almost all cancer types." (PMID 35155389, 2022). "Hence, given that cathepsin B is overexpressed in several human cancers, and may be related to tumorigenesis, oligonucleotides incorporating dipeptide linkers of the kind developed in this study may have applications as molecular probes for disease diagnosis and cancer therapy." (PMID 34953094, 2022). "Upon peptide cleavage by cathepsin B, the FRET effect wasreduced, and the enzyme activity was detectable by fluorescence whilethe photodynamic illumination at 808 nm led to cancer cell death in vivo in mouse models." (PMID 34315210, 2021). "Intracellular proteins are degraded in lysosomes by a lysosomal cysteine protease called CTSB, which controls various biological processes such as cell death, proliferation, migration, and cancer." (PMID 34769258, 2021). "Cancer cell-derived CST6 enters osteoclasts by endocytosis and suppresses the cysteine protease CTSB, leading to up-regulation of the CTSB hydrolytic substrate SPHK1." (PMID 34815788, 2021). "The most common reason leads cancer patients to death is the metastasis, thus we analyzed the impacts of expression state of CD147 and cathepsin B on overall survival of patients with HCC." (PMID 32727598, 2020).
cancer (continued). "Thus, for cell types with low cathepsin B levels or with less “leaky” endosomal-lysosomal pathways, the auristatin drugs may not be the best choice of drug to couple to E3 to generate ApTDCs against a particular cancer." (PMID 33142831, 2020). "Various types of cancer cells increase production of proteases upon increase in acidity; these include MMP2, MMP9, CTSB (cathepsin-B), and CTSL (cathepsin-L)." (PMID 32079237, 2020). "The ability of both calpain-2 and cathepsin B in inducing cell death is seen not only in CD-PCD but also in CI-PCD, making these two proteases potential targets for drug development in cancer therapy." (PMID 31969640, 2020). "In cancer cells, nuclear p-STAT3-S705 can regulate the transcription of several autophagy-related genes such as BCL2 family members (e.g., BECN1, PIK3C3, CTSB, CTSL, PIK3R1, HIF1A, and BNIP3) and microRNAs with targets of autophagy modulators." (PMID 32565533, 2019). "This study reveals a novel molecular mechanism that RD‐N promotes CTSB‐dependent DNA damage by the suppression of BRCA1 in PCa cells, leading to the identification of a potential compound that target lysosomes for cancer treatment." (PMID 30565390, 2019). "Elevation of CTSB and CTSD levels in biological fluid has been observed in patients with inflammatory diseases and many cancers." (PMID 26995190, 2016). "Surprisingly, CCK secretion by the cancer cells was found to be induced by CTSB, suggesting that CCK and CTSB contribute to an autocrine/paracrine amplification loop that mediates the mutual interplay between prostate CSCs and adipocytes." (PMID 26700819, 2016). "The vast majority of studies have evaluated the role of cathepsin B (CTSB) and its inhibitor cystatin C (CYST C) in cellular growth and angiogenesis in cancer diseases." (PMID 26904684, 2016). "One of the key pieces of evidence is the stimulation of CTSB secretion by the adipocytes, which in turn further promotes the secretion of CCK by the cancer cells." (PMID 26700819, 2016). "For example, CtsB, CtsL, and CtsS have been shown to extracellularly target the extracellular domain of E-cadherin and other adhesion molecules, thus contributing to EMT in cancer cells." (PMID 39851495, 2025). "The broad expression of CTSB and CTSL in other tissues and cell types aligns with their general role in proteolytic pathways, but their co-expression with NRP1 in macrophages hints at a cancer-specific regulatory network." (PMID 40134439, 2025). "CTSB, CTSL and CTSD were chosen due to their high expression, known function in bulk proteolysis and their reported functional importance such as cell growth and in diseases like cancer and neurodegeneration and neurodegeneration." (PMID 38775843, 2024). "Redundant functions of CTSB and CTSZ have been described in tissue homeostasis and in cancer." (PMID 38775843, 2024). "Herein, we proposed a similar strategy directed at allowing the EV cargo protein specific release in the receiving cancer (but not healthy) cells with a high cathepsin B expression." (PMID 36579638, 2023). "The discovery in this study that galectin-3 increases the secretion of Cathepsin-B, MMP-1, and MMP-13 by cancer cells suggests that increasing the secretion of proteases is probably one of the mechanisms behind galectin-3-mediated cancer promotion reported in many previous studies." (PMID 37055381, 2023). "Many potential cathepsin B inhibitors have been developed, but none of them have shown clinically available strong anticancer effects, and there currently are no FDA-approved cathepsin B inhibitors for cancer treatment." (PMID 37111617, 2023). "Our study suggests that TREM1, MAPK1, MAPK8, CTSB, MIF, and DPP4 proteins may be targeted by compounds in medicinal plants for their anti-cancer effects." (PMID 37454152, 2023). "Cathepsin B is known to be massively expressed in cancer cells, but not in healthy cells, being involved in many steps of cancer progression." (PMID 36579638, 2023).